SP1 (Sp1 transcription factor)
Diseases named in the same sentence as SP1 in open-access papers (continued):
Sharing a sentence is not in itself a finding about the gene and the disease.
glioma (continued). "To further clarify the relationship among miR-4310, PTEN, and SP1, we used in situ hybridization (ISH) and immunohistochemistry (IHC) to semi-quantitatively analyze their expression levels in 86 paraffin-embedded glioma tissue samples." (PMID 33327965, 2020). "We overexpressed SP1 in U87 and LN229 glioma cell lines and used PCR to detect the level of miR-4310." (PMID 33327965, 2020). "The feedback loop promoted glioma progression through activating the PI3K/AKT signalling, and this loop is augmented by the interaction between SP1 and c‐JUN." (PMID 32902145, 2020). "miR-4310 promotes the progression of glioma by targeting PTEN and activating the PI3K/AKT pathway; meanwhile, the expression of miR-4310 was induced by SP1." (PMID 33327965, 2020). "In the present study, we show that XIST/miR-29c coregulates SP1 and MGMT expression in TMZ-resistant glioma cell lines." (PMID 28831025, 2017). "In the present study, we monitored the protein levels of MSH6, MGMT, and SP1 in response to cotransfecting XIST and miR-29c in TMZ-resistant glioma cell lines." (PMID 28831025, 2017). "Taken together, these data suggest that XIST can inhibit miR-29c expression by directly binding to miR-29c and subsequently up-regulate the expression of SP1 and MGMT to promote the chemoresistance of glioma cells to TMZ." (PMID 28831025, 2017). "To identify which transcription factor is a potent regulator for CYP17A1 transcription in glioma, we analyzed the correlation of CYP17A1 with NFIC, Sp1, Sp3 or GATA6 in complementary DNA microarray database of glioma." (PMID 28530704, 2017). "The DDX3X protein highly expresses in human glioma cells also correlates with the protein level of SP1, and ESR1 in human glioma cell lines including LN229, U87MG, GBM8401 and U118MG as compared with normal brain tissue." (PMID 26184164, 2015). "Overexpression of SP1 is found to facilitate MMP-2-mediated cell invasiveness and predicts poor clinical outcome of glioma patients." (PMID 26177288, 2015). "IHC showed that the SNAI1 and SP1 staining of grade I to II (low grade gliomas) was weaker than that of grade III and IV (high grade gliomas) tissues." (PMID 24959930, 2014). "In the SNAI1/miR-128/SP1 axis, miR-128 acts as a negative regulator, which resist the SNAI1-promoted progression of gliomas." (PMID 24959930, 2014). "In general, our data revealed that upregulated SNAI1 accelerates glioma progression and suppresses the expression of miR-128, which can oppose SNAI1's effect and modulate SP1 expression." (PMID 24959930, 2014). "Here we demonstrate that Sp1 is critical for hypoxic-induced ADAM17, and that Sp1 contributes to hypoxic induced glioma invasion." (PMID 19772640, 2009). "Hypoxic-induced ADAM17 expression is dependent upon Sp1, and ADAM17 significantly contributes to hypoxic-induced glioma invasion." (PMID 19772640, 2009). "For instance, in glioma models, ASO-mediated knockdown of XIST could theoretically restore miR-29c activity, thereby decreasing SP1 and MGMT expression, two key mediators of chemoresistance." (PMID 41601966, 2026). "Applying this framework to human brain, liver, and testis promoters, we identified and validated clinically relevant transcription factors (TFs) in the brain, including SP1, MYC, and HES6, and confirmed their known roles in diseases such as gliomas and neuroblastomas." (PMID 41279024, 2025). "Additionally, recent studies have shown that SP1 can induce the expression of LINC01614, thereby enhancing the malignant development of gliomas through the miR‐383/ADAM12 pathway." (PMID 40735832, 2025). "We found that TRIM56 expression was directly regulated by SP1, and TRIM56 enhanced glioma cell migration and invasion via activation of CDC42, which was mediated through the interaction of TRIM56 with IQGAP1 to increase the K48-K63-linked ubiquitination transition of IQGAP1." (PMID 36870986, 2023). "Additionally, miR-331-3p, SP1 inhibitor, and PPAR-γ inhibitors can prevent the expression of NLRP6 in glioma." (PMID 37723542, 2023).
glioma (continued). "LIN00520 can be upregulated by SP1 in NSCLC, TFAP4 in glioma, and STAT3 in BC." (PMID 35309319, 2022). "Gliomas have elevated monoamine oxidase B (MAOB), SP1, and HIF-1α levels." (PMID 36077352, 2022). "In addition, transcription factors are also involved in the regulation of LINC00520, including SP1 in NSCLC, TFAP4 in glioma, and STAT3 in BC." (PMID 35309319, 2022). "A recent study revealed that XIST enhanced glioma cell chemoresistance to temozolomide via regulating miR-29c/SP1/MGMT axis, which could be a novel target for glioma treatment." (PMID 34930117, 2021). "Although U87 cells may represent an unreliable HGG model, this study suggested that SP1 may interact with the NLRP6 inflammasome to increase the malignancy, immune evasion, and radioresistance of glioma cells." (PMID 34445646, 2021). "MiR-29c regulated SP1 and MGMT expression to enhance glioma cell chemosensitivity to TMZ." (PMID 34316694, 2021). "Kaplan-Meier survival plots indicate SP1 mRNA level has negative effects on prognosis of liver hepatocellular carcinoma and brain lower grade glioma." (PMID 34257529, 2021). "Furthermore, the expression pattern of FOXO1, SP1 and c‐JUN in glioma samples and the correlations between FOXO1, c‐JUN, SP1 and miR‐5188 levels suggested an vital role of miR‐5188 in glioma development through FOXO1, c‐JUN and SP1 dysregulation." (PMID 32902145, 2020). "Besides, both SP1 and PTEN play an important role in the tumorigenesis, progression, and drug resistance of gliomas." (PMID 33327965, 2020). "Immunofluorescence showed the nuclear colocalization of SP1 and c‐JUN proteins in glioma cells." (PMID 32902145, 2020). "To confirm this, we detected SP1, Glut1 and PKM2 levels in glioma tissues." (PMID 32158359, 2020). "Sp1 was targeted by miR-421 in glioma, by miR-150-5p in colon cancer, and was not demonstrated in ovarian cancer." (PMID 33187481, 2020). "The endogenous Co‐IP assay showed the interaction between SP1 and c‐JUN in glioma cells." (PMID 32902145, 2020). "In addition, we previously unveiled signaling loops involving LRRC4, AP-2, miR-182, and LRRC4 (the LRRC4-AP-2-miR-182-LRRC4 loop) and LRRC4, miR-185, SP1, DNMT1, and LRRC4 (the LRRC4-miR-185/SP1-DNMT1-LRRC4 loop), which play important role in glioma." (PMID 32117780, 2020). "Together, we proposed that dysregulation of SP1 by miR-181b could transcriptionally induce PKM2 and Glut1, and regulate glucose metabolism in glioma." (PMID 32158359, 2020). "Intriguingly, SP1 stimulated miR‐5188‐FOXO1‐PI3K/AKT‐c‐JUN axis, thus promoting glioma development." (PMID 32902145, 2020). "As miR-150-3p decreased the expression of SP1, to detect whether miR-150-3p regulates the expression of PTEN, glioma cells were transfected with miR-150-3p mimics or control miRNA, and the protein abundance of PTEN was examined by Western blot." (PMID 29654167, 2018). "Here, we investigated whether the MMR pathway were involved in XIST/miR-29c regulation of glioma cell chemoresistance to TMZ by measuring the protein levels of MSH6, MGMT, and SP1." (PMID 28831025, 2017). "DNA repair protein O6-methylguanine-DNA methytransferase (MGMT) plays a key role in TMZ resistance; transcription factor specificity protein 1 (SP1), a regulator of DNA mismatch repair (MMR) key protein MSH6, has been reported to be up-regulated in TMZ-resistant glioma cell lines." (PMID 28831025, 2017). "To understand how miR-29c increases TMZ sensitivity in glioma cells, we conducted an RNA hybrid alignment bioinformatics search and predicted a binding site for miR-29c at the position 3584-3591 of the 3′-UTR of Sp1." (PMID 27384876, 2016). "Another activator of DR5 gene expression is the transcription factor Sp1.19, 20 However, Sp1-mediated induction of DR5 expression has not yet been reported in gliomas." (PMID 26469969, 2015).
glioma (continued). "Our findings suggest the Sp1 transcription factor mediates ADAM17 expression under hypoxia, regulates glioma invasiveness, and thus, may be a target for anti-invasion therapies." (PMID 19772640, 2009). "In addition, we examined the SP1 levels in normal and glioma tissues and the results indicated a negative relationship between miR-181b and SP1." (PMID 32158359, 2020). "Furthermore, we used univariate and multivariate COX regression to analyze whether miR-4310, SP1, and PTEN are independent prognostic factors for glioma." (PMID 33327965, 2020). "To elucidate whether Sp1-mediated CYP17A1 expression is involved in glioma development, we showed that Sp1 expression markedly increased as astrocytoma progressed to grade IV GBM and that Sp1 strongly promoted glioma invasion." (PMID 28530704, 2017). "We found that TRIM56 expression was directly transcriptionally regulated by SP1, which has not been addressed in previous studies on the role of TRIM56 in glioma." (PMID 36870986, 2023).
prostate carcinoma (98 papers, 2007 to 2026). A carcinoma that arises from epithelial cells of the prostate gland. "Another direct target of miR-361-5p is specificity protein 1 (Sp1), a transcription factor associated with the control of metabolism and autophagy, being over expressed in castration-resistant prostate cancer cells." (PMID 32102477, 2020). "Previous studies showed that increased levels of Sp1 are related to resistance to chemotherapy drugs, clinical recurrence, and tumor progression from low- to high-risk in prostate cancer." (PMID 32326583, 2020). "Because SP1 acts on gene promotor regions associated with other transcription factors, depletion of SP1 potentially reduced the interaction with twist in vascular endothelial cadherin expression in prostate cancer cells." (PMID 37894370, 2023). "Moreover, the role of AHR linked with SP1 and IL warrants further investigation in context to prostate cancer." (PMID 30972102, 2019). "Transcription factor-specific protein 1 (SP1) has been shown to be upregulated in several type of cancers; it is associated with poor prognosis and could be implicated in prostate cancer chemoprevention." (PMID 28864908, 2018). "Regarding transcription factor-driven and signaling pathway activation, SNHG4 is overexpressed under the regulation of SP1, promoting prostate cancer cell proliferation, migration, and invasion by sponging miR-377 to upregulate the oncogene ZIC5." (PMID 41301542, 2025). "A recent report showed that the DHT treatment of prostate cancer cells induced the formation of nuclear AR/Sp1 and AR/Sp3 complexes on the GPER1 gene promoter to decrease transactivation." (PMID 39858066, 2025). "Of note, there have previously been links between KLF5 expression and SP1 in breast and prostate cancers, linking elevated KLF expression with tumour suppressive functions." (PMID 39748426, 2025). "In contrast, AR/Sp1 formation on the cell surface type-A receptor 3 (EPHA3) promoter contributed to the expression of this gene which was induced by DHT in prostate cancer cell lines." (PMID 39858066, 2025). "Thiazolidinedione derivatives (OSU-CG12) have demonstrated the ability to hinder prostate cancer progression by facilitating Sp1 degradation through modulation of Sp1 phosphorylation and ubiquitination levels." (PMID 39228402, 2024). "In conclusion, TQB3720 promotes ferroptosis in prostate cancer cells by alleviating the AR/SP1 transcriptional complex." (PMID 36744249, 2023). "In view of the important role of SP1 in the transcriptional regulation of genes crucial for prostate cancer, we constructed cell lines with stable knockdown of SP1 in LNCaP-AI and C4-2 and found that silencing of SP1 decreased the expression level of METTL1." (PMID 37599359, 2023). "Previous work in prostate cancer cells similarly showed DHT-induced suppression of GPER that occurs through androgen receptor binding to transcription factors Sp1 and Sp3 and prevent their transcription of GPER." (PMID 36798163, 2023). "In this study, TQB3720 promoted ferroptosis in prostate cancer cells by alleviating the AR/SP1 transcriptional complex." (PMID 36744249, 2023). "Treatment of prostate cancer cells with mithramycin A (MitA), a natural SP1 inhibitor, led to the inhibition of EMT invasive markers and Wnt/β-cadherin signaling, alternating the metastatic ability of cells." (PMID 37894370, 2023). "Seven genes (ATM, BCL2, ERN1, FOS, NRAS, PIK3R1, and SP1) were regulated in opposite directions in patients with HD and prostate cancer." (PMID 37298337, 2023). "In prostate cancer cells, SP1 (Sp1 transcription factor) induces hypoxia-mediated autophagy to promote cancer progression." (PMID 35317831, 2022). "Among these, we focused our attention on KLF5 because several putative KLF5‐binding sites are present in the Sp1 promoter region and because a KLF5 deletion was already linked to Sp1 upregulation in a model of prostate cancer progression." (PMID 34062049, 2021).
prostate carcinoma (continued). "We also showed that TMPRSS4 promotes invasion and proliferation of lung and prostate cancer cells through transcription factors AP-1 and SP1 in a manner dependent on MAPKs." (PMID 34809669, 2021). "In the study of prostate cancer, it was found that SP1 regulates the expression of miR-3178 and affects the metastasis of prostate cancer cells." (PMID 33546692, 2021). "Natural active ingredients, terameprocol and quercetin, were found to enhance the sensitivity of NSCLC cells to radiation therapy and exert inhibitory effect on prostate cancer cells via inhibiting Sp1." (PMID 33472586, 2021). "Specificity protein (Sp) transcription factors (Sp1/Sp3/Sp4) are often overexpressed in colon cancer, pancreatic cancer, bladder cancer, breast cancer, prostate cancer, and many other cancers." (PMID 32851058, 2020). "Previously, we reported that TMPRSS4 promotes prostate cancer cell invasion and proliferation through activation of Sp1 and AP-1 transcription factors and subsequent upregulation of Slug and cyclin D111,15." (PMID 31292507, 2019). "In human prostate cancer LNCaP cells, inhibition of Sp1 activity results in a strong decrease in the AR protein level, showcasing Sp1 relevance in the regulation of AR transcription." (PMID 31404977, 2019). "Transcription factor SP1 has been reported to active MAGE-A11 expression in prostate cancer cells in a methylation-dependent manner." (PMID 29423052, 2018). "This region contains a SP1 cluster (10 embedded CpG sites) which has been reported to active MAGE-A11 expression in prostate cancer cells in a methylation-dependent manner." (PMID 29423052, 2018). "Sp1 is highly expressed in several cancers including colorectal and prostate cancer and is related to poor prognosis." (PMID 29102676, 2018). "Hsa-miR-330-3p has been demonstrated to regulate cellular motility by down regulating SP1 in prostate cancer cells, and proliferation by reducing CDC42 levels in colorectal cancer." (PMID 26967895, 2016). "Sp1 is overexpressed in a variety of cancers including liver, breast, colon, pancreas, bladder and prostate cancer, and plays an important role in cell proliferation by activating the expression of several cell cycle regulatory proteins." (PMID 27050367, 2016). "In prostate cancer, HDACis can stimulate H3 methylation and upregulate Klf4 expression via Sp1 downregulation." (PMID 25341045, 2014). "The GC-rich region within human MMP-14 promoter serves as the putative binding site for transcription factor Sp1 in fibrosarcoma and prostate cancer cells." (PMID 23394613, 2013). "It is noteworthy that we previously showed that Sp1 trans-activates FLIP in prostate cancer cells, whereas Sp3 inhibits this trans-activation." (PMID 23028678, 2012). "Previous studies show that BA induces proteasome-dependent degradation of specificity protein (Sp) transcription factors Sp1, Sp3 and Sp4 in prostate cancer cells and this study focused on the mechanism of action of BA in colon cancer cells." (PMID 21864401, 2011). "Previous studies in this laboratory showed that BA inhibits prostate cancer cell and tumor growth and this is accompanied by proteasome-dependent degradation of Sp1, Sp3 and Sp4 and several Sp-regulated pro-oncogenic gene products." (PMID 21864401, 2011). "Studies in this laboratory show that BA inhibits prostate cancer cell and tumor (xenograft) growth and this is due, in part, to proteasome-dependent downregulation of Sp1, Sp3, Sp4 and several Sp-regulated genes." (PMID 21864401, 2011). "This is in contrast to the methylation pattern identified in DLC1 in human prostate cancer in which the Sp1 sites are more heavily methylated, contributing to silencing." (PMID 19912643, 2009). "Evolutionary conserved WT1 and SP1 sites in the PSA promoter were confirmed by ChIP to bind both WT1 and SP1 in LNCaP prostate cancer cells chromatin." (PMID 18631392, 2008).